ECEL1 (endothelin converting enzyme like 1)
Description:
May contribute to the degradation of peptide hormones and be involved in the inactivation of neuronal peptides.
Synonyms: XCE; DINE; DA5D; ECEX
Tractability: Antibody: its Gene Ontology location is reachable by antibodies, with high confidence; UniProt predicts a signal peptide or a membrane-spanning region.
Gene: Protein-coding gene on chromosome 2 (232,479,825 to 232,489,045, reverse strand). Ensembl gene ENSG00000171551.
Subcellular location: Membrane
Subcellular location (Human Protein Atlas): Nucleoplasm; Nuclear membrane; Nucleoli
Gene Ontology:
Molecular function: metalloendopeptidase activity; metallopeptidase activity
Biological process: neuropeptide signaling pathway; protein processing; respiratory system process; proteolysis
Cellular component: plasma membrane; membrane
Genetic constraint (gnomAD): Loss-of-function variants: 87 observed, 94.61 expected, observed/expected ratio (o/e) 0.92, 90% interval 0.77 to 1.1. The upper end of that interval is the gene's LOEUF score, 1.1, which puts it in group 4 of 6, group 1 being the genes least tolerant of losing a copy. Missense variants: 1,032 observed, 996.41 expected, observed/expected ratio (o/e) 1.04, 90% interval 0.98 to 1.09. Synonymous variants: 487 observed, 412.58 expected, observed/expected ratio (o/e) 1.18, 90% interval 1.1 to 1.27.
Homologues: Orthologues: chimpanzee ECEL1 (99% identical), macaque ECEL1 (99% identical), dog ECEL1 (96% identical), pig ECEL1 (96% identical), rabbit ECEL1 (95% identical), rat Ecel1 (95% identical), mouse Ecel1 (95% identical), guinea pig ECEL1 (94% identical), tropical clawed frog ecel1 (73% identical), zebrafish ecel1 (58% identical), Drosophila melanogaster Nep3 (34% identical), Drosophila melanogaster Nep4 (34% identical), and 20 more. Paralogues in human: ECE2 (37% identical), ECE1 (37% identical), MMEL1 (35% identical), MME (34% identical), PHEX (29% identical), KEL (26% identical).
Diseases named in the same sentence as ECEL1 in open-access papers:
ECEL1 is named in the same sentence as 31 diseases in open-access papers, as found by Europe PMC text mining. Sharing a sentence is not in itself a finding about the gene and the disease. The quoted sentences say what the papers report.
arthrogryposis (3 papers, 2021 to 2023). A rare, non-progressive congenital disorder characterized by multiple joint contractures which are present at birth. "Subjects with ECEL1 variants display congenital distal arthrogryposis together with variably penetrant combinations of ptosis, strabismus, and ophthalmoplegia, similar to subjects with the TUBB3 R262H syndrome." (PMID 34652576, 2021). "Variants in ECEL1, which encodes the endothelin-converting enzyme like-1, were identified in the recessive state in several families with DA5D, a rare form of arthrogryposis in which affected individuals have contractures as well as distinctive facial features and ptosis." (PMID 34203046, 2021).
distal arthrogryposis (3 papers, 2017 to 2024). A muscle tissue disease characterized by congenital joint contractures of hand and feet. "Recently, it has also been shown of particular interest in TPM2-related myopathies and in certain forms of distal arthrogryposis such as that due to ECEL1 mutations." (PMID 36968005, 2022). "Endothelin-converting enzyme-like 1 (ECEL1, also termed DINE in rodents), a membrane-bound metalloprotease, has been identified as a gene responsible for distal arthrogryposis (DA)." (PMID 29132416, 2017).
ophthalmoplegia (3 papers, 2017 to 2021). Weakness or paralysis of at least one of the muscles controlling the movement of the eye. "Notably, distal arthrogryposis type 5 can be associated with blepharophimosis, ptosis and ophthalmoplegia, and one genetic cause is biallelic variants in the endothelin-converting enzyme-like 1 (ECEL1) gene." (PMID 34652576, 2021). "Our patient suffered from distal joint contractures, unilateral ptosis, and strabismus, without ophthalmoplegia, and molecular genetics testing confirmed his compound heterozygous ECEL1 mutations." (PMID 32566668, 2020).
distal arthrogryposis type 5D (2 papers, 2013 to 2020). "For example, ECEL1 is a gene responsible for distal arthrogryposis type 5D with similar limb anomalies observed in our patients." (PMID 24000153, 2013).
acute myeloid leukemia (1 paper, 2022). Acute myeloid leukemia (AML) is a group of neoplasms arising from precursor cells committed to the myeloid cell-line differentiation. "Further, an in-depth literature analysis revealed that several of these genes play important roles in cancer (CDCA3, ECEL1, EN1, HLA-DMB, SPRR2A, TMEM40) including acute myeloid leukemia (CDCA3, HLA-DMB, RPL18A, PF4, PRG3) and T cell acute lymphoblastic leukemia (TLX3)." (PMID 35008420, 2022).
arthrogryposis multiplex congenita (1 paper, 2022). Arthrogryposis multiplex congenita (AMC) is a group of disorders characterized by congenital limb contractures. "A series of autosomal recessive mutations in ECEL1 have been documented to cause arthrogryposis multiplex congenita (AMC), a common type of congenital contracture disorder." (PMID 36360333, 2022).
Escobar syndrome (1 paper, 2021). "The evolution of the phenotype through the years was crucial to guide the diagnosis: DA5D in pt 9, with billelic variants in ECEL1 that met the ACMG criteria of pathogenicity, and Escobar syndrome in pt 10, with a known pathogenic homozygous variant in CHRNG." (PMID 35052370, 2021).
glioma (1 paper, 2019). A benign or malignant brain and spinal cord tumor that arises from glial cells (astrocytes, oligodendrocytes, ependymal cells). "ECEL1 and GRTP1 did not demonstrate significant downregulation in any of the subtypes of human glioma." (PMID 31475119, 2019).
hypogonadism (1 paper, 2022). A disorder characterized by decreased function of the gonads. "Furthermore, mutations in the genes ECEL1 and LHB, are associated with skeletal muscle and limb anomalies as well as hypogonadism." (PMID 36421828, 2022).
peripheral nerve injury (1 paper, 2025). Injury to a peripheral nerve. "We demonstrated that blocking the increased expression of ECEL1 in the DRG caused by peripheral nerve injury could decrease the high excitability of injured DRG neurons and attenuate nociceptive sensation." (PMID 40904192, 2025).
schizophrenia (1 paper, 2025). A major psychotic disorder characterized by abnormalities in the perception or expression of reality. "Conversely, dysfunction in somatostatin-positive and Ecel1+ neurons, endowed with smaller T-currents and lower frequency bursts, may contribute to the cognitive and emotional symptoms associated with schizophrenia." (PMID 40995120, 2025).
Spinocerebellar ataxia type 43 (1 paper, 2023). "Even the neuropeptide activator Pcsk1 and its inhibitor Pcsk1n, as well as neuropeptide inactivators like Mme (which is responsible for Spinocerebellar Ataxia type 43) and Ecel1 were upregulated." (PMID 37830614, 2023).
cancer (2 papers, 2012 to 2022). A tumor composed of atypical neoplastic, often pleomorphic cells that invade other tissues. "The remaining other 4 genes, VAX1 KCNV1, ECEL1 and TMEM26, were found in the present study to be hypermethylated in BC, but there were no any background record that provided mechanisms in the carcinogenesis and development of any cancer, let alone BC." (PMID 22529986, 2012).
neuromuscular disease (2 papers, 2015). "Within this cohort, mutations were found in eight previously known neuromuscular disease genes (CHRND, CHNRG, ECEL1, GBE1, MTM1, MYH3, NEB and RYR1) and four novel neuromuscular disease genes were identified and have been published as separate reports (GPR126, KLHL40, KLHL41 and SPEG)." (PMID 26578207, 2015). "Mutations were found in eight previously known neuromuscular disease genes (CHRND, CHNRG, ECEL1, GBE1, MTM1, MYH3, NEB and RYR1) and four novel neuromuscular disease genes (GPR126, KLHL40, KLHL41 and SPEG)." (PMID 26933539, 2015).
myopathies (1 paper, 2022). "Moreover, WBMRI has recently been shown to be of particular interest in TPM2-related myopathies an in certain forms of distal arthrogryposis such as DA10 or arthrogryposis due to ECEL1 mutations but has not been used in DA2B yet." (PMID 36968005, 2022).
tumor (1 paper, 2012). "The methylation status of ECEL1 and TMEM26 was significantly related to a high degree of tumor differentiation, with HR = 2.43 (95% CI, 1.19 to 4.97; P = 0.01) and 2.32 (95% CI, 1.11 to 4.85; P = 0.03), respectively, suggesting that they are involved in BC malignancy and progression." (PMID 22529986, 2012).
ECEL1 also shares sentences with these, for which no sentence is quoted: ptosis (3 papers); Strabismus (2); achondroplasia (1); asphyxiating thoracic dystrophy 3 (1); Ataxia (1); Blepharophimosis (1); cerebellar ataxia (1); distal arthrogryposis type 5 (1); Duane-radial ray syndrome (1); multiple pterygium syndrome (1); neuroblastoma (1); osteogenesis imperfecta type 1 (1); ovarian carcinoma (1); respiratory failure (1); Telangiectasia (1).